TNF (tumor necrosis factor)
Diseases named in the same sentence as TNF in open-access papers (continued):
Sharing a sentence is not in itself a finding about the gene and the disease.
delirium (continued). "We also recently reported that delirium patients showed negative correlations between age and DNAm level in several CpG sites on the TNF gene." (PMID 34887385, 2021). "Compared to patients without delirium, delirious patients exhibited reduced release of TNFα, IP-10, IL-1β, IL-6, and IL-12 after whole blood stimulation with LPS." (PMID 29669581, 2018). "Delirious patients had reduced release of TNFα, IP-10, and IL-12 and increased release of IL-8 compared to patients without delirium." (PMID 29669581, 2018). "The findings suggested that TNF-α might not function as an initiating factor but rather as a response to the inflammatory cascade during delirium." (PMID 37649721, 2023). "The results of this study showed that the levels of preoperative cerebrospinal fluid IL-1β and TNF-α were higher in delirium than in non-delirium patients, suggesting that patients with high levels of preoperative neuroinflammation are prone to delirium postoperatively." (PMID 35294925, 2022). "The plasma level of IL-6, but not TNFα, was higher in patients with delirium." (PMID 29669581, 2018). "Inflammatory markers such as IL-6, IL-2, TNF-α, and C-reactive protein have been found to be elevated in POD patients compared to those without delirium." (PMID 40092071, 2025). "Patients with delirium differed significantly from those without delirium in age, TBI classification, sleep duration, CRP levels, TNF-α levels, pain, self-efficacy, and insomnia (P < 0.05)." (PMID 39554848, 2024). "For example, one study showed increased IL-6, IL-2, and IL-1α levels in delirium due to septic shock, although no such increases in CRP, CXCL8 and TNF-α could be established." (PMID 35641947, 2022).
encephalitis (91 papers, 2009 to 2026). An acute inflammatory process affecting the brain parenchyma. "Elevated S-CKs levels can serve as diagnostic indicators for acute viral encephalitis in children; there are reports of high levels of TNF-α and IL-6 in the CSF." (PMID 39995678, 2025). "We chose markers that have already been associated with viral encephalitis and neurodegenerative diseases, including tumor necrosis factor alpha (TNFα), interleukin 6 (IL6), and interleukin 1 β (IL1β)." (PMID 33407600, 2021). "We previously demonstrated that DENV infection causes overt TNF-α production during the progression of viral encephalitis." (PMID 33072626, 2020). "Increased serum levels of pro-inflammatory cytokines, IFN-γ, IL-6, and TNFα are observed in patients with EV71-associated encephalitis and pulmonary edema compared to patients with uncomplicated HFMD." (PMID 26181772, 2015). "Studies of other encephalitis-associated viruses have shown that IFNγ and TNFα can play a critical role in controlling viral replication in the CNS." (PMID 24922480, 2014). "The present study is to determine the role of polymorphism of TNF-alpha promoter regions at positions -238G/A, -308G/A, -857C/T and -863C/A in the severity of Japanese encephalitis patients." (PMID 22276993, 2012). "The encephalitis in the TNF-transgenic mice has most likely also increased the risk for seizures by altering excitability of neurons or neuromodulatory responses as shown for other seizure models." (PMID 22848506, 2012). "A combination of liver dysfunction resulting in hyperammonia, combined with elevated cytokines including TNF-α, which are known to cause neuronal loss and brain injury, could result in a lethal encephalitis." (PMID 35587473, 2022). "A combined effect of prolonged exposure to high level of pro-inflammatory cytokines (TNF-α) combined with reduced release of anti-inflammatory cytokines IL-10 and IL-4 in encephalitis conditions may cause immunologic imbalance landed with poor prognosis." (PMID 22276993, 2012). "Inhibition of IL-1 and TNF-α has been reported to reduce neuroinflammation and improve outcomes in animal models of viral encephalitis." (PMID 41221080, 2025). "This meta-analysis provides evidence for higher CSF concentrations of IL-6, IL-8, IL-10, CXCL10, and TNF-α in encephalitis patients compared to controls." (PMID 36048783, 2022). "Increased CSF concentration of the TNF-α was seen in the meta-analysis of 213 encephalitis patients and 73 controls (SMD, 2.61; 95% CI, 1.29–3.94; P < 0.001)." (PMID 36048783, 2022). "The meta-analysis demonstrated that the concentration of the TNF-α is increased in the encephalitis patients compared to controls (npatients = 144; ncontrol = 106; SMD, 9.06; 95% CI, 2.85–15.27; P < 0.01)." (PMID 36048783, 2022). "A clinical study found that the serum levels of eotaxin, IFN- γ, IL-15, IL-6, IP-10, and TNF-α in the confirmed encephalitis patients were elevated remarkably before clinical deterioration, which might be related to a potential association with the development of encephalitis." (PMID 35782112, 2022). "Proinflammatory factors IL-6, TNF-α, IL-1β were found significantly higher in patients with encephalitis and NPE than those with mild disease." (PMID 36386168, 2022). "sCD146 levels in the CSF of patients with the acute stage anti-NMDAR encephalitis were significantly increased compared with controls and accompanied by increases in TNF-α, IL-6 and IL-10." (PMID 34220828, 2021). "A significant increase in the levels of tumor necrosis factor-α (TNF-α) in CSF of the children with influenza-related encephalitis and encephalopathy was reported by Togashi (1999)." (PMID 34764869, 2021).
encephalitis (continued). "At the same time, our findings regarding OPN, IL-6, IL-10, and TNF-α raise the question of possible involvement of T cells in anti-NMDAR encephalitis." (PMID 33250837, 2020). "Compared to WT mice, TNF-/- mice fail to control T. gondii growth during chronic infection and succumb significantly earlier to encephalitis." (PMID 32628723, 2020). "Transgenic mice over-expressing human tumor necrosis factor (TNF)-α have been utilized to demonstrate the role of TNF-α in the development of DENV encephalitis-like symptoms and neurotoxicity." (PMID 30871179, 2019). "In the present work, we showed that a chronic infusion of TNF-α into the central nervous system decreased NMDAR-mediated EPSCs in the hippocampal neurons, suggesting that amplification of TNF-α likely worsens dysfunction of NMDARs in anti-NMDAR encephalitis." (PMID 31297084, 2019). "Following CHPV infection expression levels of TNF-a, CCL2 and IL-6 were found to increase that was previously implicated in playing decisive roles in encephalitis has decreased significantly after (-)-25b treatment." (PMID 30001342, 2018). "We found that SDG diminished leukocyte adhesion to and migration across the BBB in vivo in the setting of aseptic encephalitis (intracerebral TNFα injection) and prevented enhanced BBB permeability during systemic inflammatory response (LPS injection)." (PMID 29373982, 2018). "To further assess effects of PARP inhibition on leukocyte adhesion/migration, we used IVM in PARPko and WT mice, utilizing systemic LPS-induced inflammation and TNFα-mediated encephalitis (by IC injection)." (PMID 27677851, 2016). "Wang and Dong measured cerebrospinal fluid NO and TNF-α levels in three children groups suffering from viral encephalitis, febrile seizures, and ordinary trauma, respectively." (PMID 25587341, 2014). "The concentrations were higher in the viral encephalitis group than in the febrile seizures group and ordinary trauma group, which shows NO and TNF-α participate in inflammation of the CNS." (PMID 25587341, 2014). "The elevation of IL-12(p70), FGF-2, PDGF-BB, and TNF-α levels in the patients with encephalitis indicated clear contrast with the normal findings in those with sCJD." (PMID 24219883, 2013). "In contrast, levels of classical proinflammatory cytokines such as IL-12(p70) and tumor necrosis factor-α were increased only in encephalitis." (PMID 24219883, 2013). "In TNF-α KO mice, we showed that the increased levels of inflammatory cytokines including Fas and the granular exocytosis correlated with severe encephalitis and fatal outcome." (PMID 23940775, 2013). "This correlated with lower weight gain, stronger degree and progression of encephalitis and early, strong microglia activation in the TNF-transgenic mice, most obviously in homozygous animals." (PMID 22848506, 2012). "Significant or minor change of blood TNF-α in EV71 patient with both encephalitis and PE was reported by different clinical studies." (PMID 22994237, 2012). "Consistent with clinical features of EV71 patients with encephalitis and PE, who are presented with higher levels of the proinflammatory cytokines in blood, IL-6, IL-1β and TNF-α were induced in EV71-infected MDMs." (PMID 22994237, 2012). "We found increased levels of TNF-α in mouse brain tissue just before the onset of clinical signs of encephalitis." (PMID 21388530, 2011). "During viral encephalitis, MMPs can affect inflammatory responses by processing molecules like TNF-α, mediating transmigration of leukocytes and the development of CNS damage." (PMID 21388530, 2011). "When PD‐1 blockade restores T‐cell function, excessive TNF‐α production may trigger neuroinflammatory cascades that ultimately manifest as encephalitis, myasthenia gravis, and cranial nerve disorders documented in our analysis." (PMID 41489356, 2026).
encephalitis (continued). "Additionally, the use of IL-23 inhibitors correlates with a reduced incidence of infections and malignancies in comparison to anti-TNF-α therapy, with significantly reduced risks of certain pathologies, such as encephalitis." (PMID 40283885, 2025). "Furthermore, microglia infected with JEV exhibit high level of glutamate and TNF-α, thereby promoting the excitotoxic neuronal death and exacerbating encephalitis." (PMID 39844330, 2025). "A recent study demonstrated the crucial role of TNF in viral encephalitis." (PMID 40285022, 2025). "Additionally, as a pro-inflammatory cytokine, TNF-α levels were significantly elevated in anti-NMDAR encephalitis patients." (PMID 39450046, 2024). "Some studies have reported that influenza viruses result in encephalitis and encephalopathies, as the related neuronal cells release potentially cytotoxic substances such as TNF‐α, IL‐1β, oxygen radicals and nitric oxide, which also trigger apoptosis and autophagy in the infected cells." (PMID 38683122, 2024). "TNF-α is increased in the CSF of patients with anti-NMDAR encephalitis." (PMID 35937071, 2022). "Increased serum levels of TNF-α were observed in patients with encephalitis." (PMID 36048783, 2022). "Because EV71 patients with encephalitis have been reported to have increased TNFα and IL-6 levels, we also investigated whether the gliosis-associated inflammatory markers would also be decreased in sera collected from these mice treated with the antibody." (PMID 35399111, 2022). "Interleukins, chemokines and TNF-α were increased in encephalitis cases." (PMID 35239818, 2022). "In addition, the serum/plasma levels of the TNF-α were increased in encephalitis patients, but serum/plasma concentration of the IL-6, IL-10, CXCL10, and CXCL13 remained unchanged." (PMID 36048783, 2022). "Influenza virus may lead to encephalitis and encephalopathy by activating glial cells to release potential cytotoxic substances, such as TNF-α, IL-1β, NO, and oxygen-free radicals." (PMID 33953861, 2021). "Based on this hypothesis, we have previously verified that the target TNF-α could reduce the occurrence of DENV-induced encephalitis-like symptoms in mice." (PMID 34831405, 2021). "Interestingly the C genotype isolate from HFMD patient induced higher amount of TNF-α than the encephalitis patient." (PMID 34493781, 2021). "TNF is an early proinflammatory cytokine that is rapidly expressed by microglia, and infiltrating monocytes upon CNS infection and plays a key role in protecting from viral encephalitis." (PMID 32133008, 2020). "Tumor necrosis factor (TNFα) is another example of a key pro-inflammatory cytokine that is involved in neuroinflammation, and yet also acts to control infection and prevent encephalitis." (PMID 30167845, 2018). "The elevated levels of IL-10, IL-6, IL-8, TNFα (cytokines) and CCL2 and CXCL9 (chemokines) in monocytes may help in predicting the pathogenicity of CHPV causing encephalitis and possible entry into the central nervous system." (PMID 27628855, 2016). "Similarly, following peripheral infection with herpes simplex virus, production of TNF protected mice from development of severe encephalitis." (PMID 24922480, 2014). "It was previously reported in Sindbis virus-induced encephalitis that the infected astrocytes in the brain may be the source of pro-inflammatory cytokines such as IL-6 and TNF-α." (PMID 24086645, 2013). "Thus, the encephalitis in the TNF-transgenic mice most likely represents one important key factor for seizure induction." (PMID 22848506, 2012). "In addition, it has recently been shown that the resolution of pathology following virus-induced encephalitis requires TNFα for repair in the striatum and the hippocampus through TNFR1 and TNFR2 respectively." (PMID 21812954, 2011).
encephalitis (continued). "It was also noted that the levels of serum eotaxin, IFN-γ, IL-15, IL-6, IP-10, and TNF-α were significantly elevated before clinical deterioration in the confirmed encephalitis patient, suggesting the roles of these cytokines in the development of encephalitis." (PMID 35782112, 2022). "For instance, βArr2 inhibited the pro-inflammatory cytokines TNF-α and IL-6 and activation of transcription factor NF-κB, increased the expression of anti-inflammatory cytokines IL-10 and IL-4 in microglia for enhancing neurological function in encephalitis mice." (PMID 34787064, 2022). "C57BL/6J transgenic mice overexpressing human tumor necrosis factor (TNF) and infected with DENV, developed neurological symptoms, and treatment with anti TNF-antibodies reduce mortality suggesting that intervention of this pathway may be used to treat DENV encephalitis." (PMID 31979145, 2020). "However, while TNFα plays a major role in attracting immune cells and thereby boosting inflammation that may lead to rabies-encephalitis, the direct impact of TNFα on BBB integrity remains controversial." (PMID 27336830, 2016). "Furthermore, from the results of increased fatality in TNF-α KO mice, we propose that increased levels of TNF-α in the brains of severe cases in WT mice were probably produced in response to the disease severity, to alleviate the pathological impact of the encephalitis." (PMID 23940775, 2013). "Meanwhile, key inflammatory mediators (MCP1, IL1β, IL6, TNFα) were significantly elevated in NCG-hSTAT2+/+ mice during viral neuroinvasion, likely driving encephalitis pathogenesis." (PMID 40855992, 2025). "In a protozoan-induced mouse encephalitis model, iNOS, TNF, and IFN-γ levels were elevated and encephalitis increased in ST2-knockout mice." (PMID 36291105, 2022). "This meta-analysis serves as evidence that encephalitis patients had greater CSF concentrations of IL-6, IL-8, IL-10, CXCL10, and TNF-α when compared to controls." (PMID 36048783, 2022). "According to the analyses, patients with encephalitis had higher CSF amounts of IL-6, IL-8, IL-10, CXCL10, and TNF-α than healthy controls." (PMID 36048783, 2022). "In patients with viral encephalitis and controls, we only found significant correlations between OPN and TNF-α (r = 0.632, p = 0.021) in the viral encephalitis patients and IL-10 and TNF-α in the controls (r = 0.617, p = 0.019)." (PMID 33250837, 2020). "We observed that TNF-α, IL-10, IFN-α, IL-6, CXCL10 and CXCL13 demonstrated >79.1% sensitivity in patients with encephalitis using control 95th centile as cut off (specificity 95%)." (PMID 27575749, 2016). "In descending order, CSF TNF-α, IL-10, IFN-α, IL-6, CXCL13 and CXCL10 had the best sensitivity (>79.1%) when all encephalitis patients were included." (PMID 27575749, 2016). "In our cohort of encephalitis, the Th1 (CXCL10 & TNF-α), T reg (IL-10), B cell (CXCL13) related cytokine/chemokines, and cytokines with broad spectrum of activities including IL-6 and IFN-α, were elevated in more than 75% of the cases." (PMID 27575749, 2016). "High levels of proinflammatory cytokines, such as Interleukin 6 (IL-6), Tumor necrosis factor α (TNF-α) and Interleukin-1β (IL-1β), have been found in EV-A71 patients with pulmonary edema (PE) and encephalitis." (PMID 25412347, 2014). "In the case of WNV encephalitis in mice, increased BBB permeability induced by TNF-α allows WNV to cross into the CNS." (PMID 21629771, 2011). "In the same study, the pharmacological blockade of TNF-α was shown to partly retard DENV-induced M1 polarization, suggesting a potential therapeutic strategy for mitigating the severity of flavivirus-induced encephalitis." (PMID 39940721, 2025). "Furthermore, in spite of the protective role of TNF-α, excessive production of TNF-α can exacerbate inflammation and lead to immunopathology, contributing to the symptoms of acute toxoplasmosis, such as encephalitis." (PMID 40663568, 2025).